Y_RNA (Y RNA )
Gene: Miscellaneous RNA gene on chromosome 5 (17,117,576 to 17,117,686, reverse strand). Ensembl gene ENSG00000206814.
Homologues: Orthologues: chimpanzee Y_RNA (99% identical), macaque Y_RNA (92% identical). Paralogues in human: RNY1 (90% identical), Y_RNA (89% identical), Y_RNA (88% identical), Y_RNA (87% identical), Y_RNA (86% identical), RNY1P11 (86% identical), Y_RNA (85% identical), RNY1P8 (84% identical), Y_RNA (84% identical), RNY1P10 (83% identical), Y_RNA (83% identical), RNY1P7 (82% identical), and 97 more.